METTL3 (methyltransferase 3, N6-adenosine-methyltransferase complex catalytic subunit)
Diseases named in the same sentence as METTL3 in open-access papers (continued):
Sharing a sentence is not in itself a finding about the gene and the disease.
psoriasis (5 papers, 2022 to 2025). An autoimmune condition characterized by red, well-delineated plaques with silvery scales that are usually on the extensor surfaces and scalp. "Collectively, these data suggested that knockout of Mettl3 in macrophages alleviated psoriasis‐like phenotype in mice." (PMID 40679079, 2025). "Conditional knockout of Mettl3 in macrophages alleviated psoriasis‐like symptoms in mice, whereas knockout of Alkbh5 exacerbated them." (PMID 40679079, 2025). "STM2457, a selective inhibitor of METTL3 enzymatic activity, was used to treat macrophages derived from the peripheral blood of healthy donors and psoriasis patients." (PMID 40679079, 2025). "Our experiments verified that the mRNA level of YTHDC2 was elevated in psoriasis patients, and the expression of METTL3 and IGF2BP2 was significantly decreased." (PMID 38436011, 2024). "And they found the decrease of METTL3-mediated m6A methylation promoted the development of psoriasis in imiquimod-induced psoriasis-like mouse model (Wang, Huang & Jin, 2022)." (PMID 38436011, 2024). "Further, compared with mice heterozygous for METTL3 knockout, wild-type control mice showed ameliorated psoriasis-like clinical and pathological manifestations." (PMID 37671161, 2023). "Inhibiting m6A methylation by knocking down Mettl3 promoted the development of psoriasis and increased its severity in imiquimod-induced (IMQ-induced) psoriasis-like model mice." (PMID 36293529, 2022). "Consistent with the results from human samples, the expression of Mettl3 in the IMQ-induced psoriasis-like mice was significantly lower than that in matrix-exposed mice, as assessed by reverse-transcription quantitative PCR (RT-qPCR) and western blotting." (PMID 36293529, 2022). "On day 7, at the peak of psoriasis-like changes, we observed that the splenomegaly of mice in the Mettl3+/− group was more pronounced than that in the Mettl3+/+ group." (PMID 36293529, 2022). "Inhibiting m6A methylation by knocking down Mettl3 promoted the development of psoriasis and increased its severity in imiquimod-induced psoriasis-like model mice." (PMID 36293529, 2022). "Inhibiting m6A methylation by knocking down Mettl3 increased acanthosis, the proportion of Th17 cells, and inflammatory cell infiltration in the psoriasis-like mouse model." (PMID 36293529, 2022). "To study the functional correlation of METTL3 downregulation with the development of psoriasis, we applied 5% imiquimod cream on the back of mice for 7 consecutive days and sacrificed the mice at 4, 7, and 10 days." (PMID 36293529, 2022). "In this study, we found that m6A methylation and Methyltransferase-like 3 (METTL3) were both downregulated in psoriatic skin lesions and were negatively correlated with Psoriasis Area and Severity Index (PASI) scores." (PMID 36293529, 2022). "In our study, we found that the reduction of METTL3-mediated m6A methylation exacerbated the development of psoriasis vulgaris in an IMQ-induced psoriasis-like mouse model." (PMID 36293529, 2022). "Interestingly, genes with differential m6A modification in Mettl3 cKO and Alkbh5 cKO relative to WT were enriched in psoriasis‐related pathways, including JAK‐STAT signaling pathway, Th17 cell differentiation, and Interleukin‐1 beta production." (PMID 40679079, 2025). "Notably, treatment with the METTL3 inhibitor markedly attenuated M1 polarization in psoriasis‐derived macrophages." (PMID 40679079, 2025). "Moreover, KEGG analysis suggests that METTL3 may play a role in the pathogenesis of psoriasis through the WNT pathway." (PMID 37671161, 2023). "A significant reduction in the psoriasis area and severity index (PASI) score of IMQ‐treated Mettl3 cKO mice was observed." (PMID 40679079, 2025). "RT-qPCR results in the skin specimen showed that YTHDC2 was highly expressed in the psoriasis and IMQ group compared to the controls, while METTL3 and IGF2BP2 were decreased in the disease group, which was consistent with the results in GSE30999." (PMID 38436011, 2024).
steatosis (5 papers, 2021 to 2023). Increased lipid within the cytoplasm of cells. "Loss of m6A writer protein WTAP or METTL3 in hepatocytes enhances hepatic steatosis, inflammation, and activation of STAT3 and ERK signaling pathways, which exacerbates the course of DEN-induced HCC." (PMID 37777158, 2023). "Hepatic perinatal loss of Mettl3 causes severe liver damage, including steatosis, apoptosis, and fibrosis, and finally results in lethality within 7 weeks." (PMID 35931692, 2022). "The loss of Mettl3 in the liver leads to more-pronounced steatosis, steatohepatitis, and collagen deposition, which suggests a robust fibrosis progression, whereas overexpression of Mettl3 in the liver induces the opposite effects." (PMID 34893641, 2021). "Changes in the expression of METTL3 are reported to be related to steatosis, but opinions on the regulation of steatosis by METTL3 different." (PMID 37710320, 2023). "PCR and Western Blot suggested METTL3 expression was upregulated in the fatty liver and in steatosis HepG2 cells, indicating the potential role of METTL3 in NAFLD." (PMID 37710320, 2023). "Knocking out Mettl3 perinatally with Alb-Cre (Mettl3 cKO) induces apoptosis and steatosis of hepatocytes, results in severe liver injury, and finally leads to postnatal lethality within 7 weeks." (PMID 35931692, 2022). "However, whether METTL3 coordinates steatosis and inflammation to mediate the NAFL-to-NASH transition is largely unknown." (PMID 34893641, 2021). "Our results showed that the expression of METTL3 was increased in a mouse model of NAFLD induced by HFD feeding, which is consistent with the FFA-induced steatosis of HepG2 cells." (PMID 37710320, 2023).
stomach cancer (5 papers, 2021 to 2023). "IGF2BP3 directly recognizes and binds to the m6A modification site of METTL3-mediated HDGF mRNA and enhances the stability of HDGF, thereby promoting gastric tumor angiogenesis." (PMID 35572524, 2022).
Stroke (5 papers, 2024 to 2025). Sudden impairment of blood flow to a part of the brain due to occlusion or rupture of an artery to the brain. "Augmenting this pathway via METTL3 represents a promising therapeutic strategy to attenuate ferroptosis and preserve the brain after stroke." (PMID 38302612, 2024). "While previous studies have partially confirmed the involvement of METTL3 in stroke regulation, our study is the first to elucidate the regulatory mechanism of METTL ferroptosis pathway and its association with ubiquitination." (PMID 38302612, 2024). "At present, several studies have shown that METTL3 has the potential to regulate ANXA-mediated immune microenvironment after stroke." (PMID 38302612, 2024). "In mouse stroke models, we found METTL3 overexpression increased NEDD4L levels, enhanced TFRC ubiquitination and degradation, limited iron accumulation, and reduced oxidative damage and ferroptotic cell death, resulting in smaller infarct sizes and improved neurological function." (PMID 38302612, 2024). "Given that silencing METTL3 attenuates OGD/R-induced neuronal cytotoxicity, STM2457 may also have clinical benefits in stroke treatment." (PMID 40591025, 2025). "As NEDD4L suppresses ferroptosis and iron-mediated neuronal death after stroke by ubiquitinating the iron transporter TFRC, we explored whether boosting METTL3 could protect the brain against ischemia through modulating the NEDD4L-TFRC pathway." (PMID 38302612, 2024).
testicular germ cell tumor (5 papers, 2020 to 2023). A germ cell tumor arising from the testis. "In testicular germ cell tumors, METTL3 promotes the m6A-modified transcription factor-activating enhancer-binding protein 2C (TFAP2C) mRNA to regulate cisplatin treatment." (PMID 34001850, 2021). "In testicular germ cell tumors (TGCT), METTL3 expression was significantly downregulated in TGCT tissues, and its level correlated positively with patient survival rates and levels of tumor-infiltrating CD8+ T cells, CD4+ T cells, and NK cells." (PMID 35296338, 2022). "Some studies have shown that METTL3, ALKBH5, YTHDC1, YTHDF1, YTHDF2, and HNRNPC are the main m6A-related genes in type II testicular germ cell tumors." (PMID 32258108, 2020).
acute leukemia (4 papers, 2021 to 2024). A clonal (malignant) hematopoietic disorder with an acute onset, affecting the bone marrow and the peripheral blood. "For example, in cellular and animal studies, STM2457, a small molecule active inhibitor of METTL3, inhibits acute leukemia development caused by elevated m6A levels." (PMID 38562618, 2024). "STM2457 is a novel, highly selective, orally active METTL3 inhibitor, that has been previously reported in a study of acute leukemia." (PMID 36932427, 2023). "Therefore, we conclude that METTL3 likely plays a role in sustaining the expression of c-Myc and BCL2 in specific acute leukemia cells, particularly implicating its involvement in c-Myc regulation." (PMID 40453361, 2024).
autism (4 papers, 2024 to 2025). Persistent deficits in social interaction and communication and interaction as well as a markedly restricted repertoire of activity and interest as well as repetitive patterns of behavior. "Another downregulated gene is the RNA-methylating enzyme METTL3, previously reported to be regulated by the β-catenin/WNT signaling pathway in an autism mouse model, as well as by the FMR1 gene, causative of the autistic Fragile X syndrome." (PMID 38637827, 2024). "In the hippocampal tissues of mouse models of autism, METTL3 stabilizes MALAT1 expression by increasing m6A modification of the host gene." (PMID 39344412, 2024). "At this stage, METTL3 inhibits autism-like symptoms and the death of hippocampal neurons." (PMID 39344412, 2024).
autoimmune disorders (4 papers, 2021 to 2024). "Conditional deletion of Mettl3 or Mettl14 in murine CD4+ T cells impairs T cell differentiation and homeostasis, while mice lacking Mettl3 or Mettl14 specifically in Treg cells displayed severe autoimmunity despite normal numbers of Foxp3+ Treg cells." (PMID 37307819, 2024).
Breast Invasive Carcinoma (4 papers, 2022 to 2025). "Within the TCGA Breast Invasive Carcinoma PanCancer Atlas dataset (n = 996) mutations of METTL3, METTL14 and CBLL1 were uncommon, with amplifications being the most common genetic alteration." (PMID 41310336, 2025). "Additionally, COMMD4_AS1, GNAS, POLDIP3, FASTK, and RHOC AS were significantly associated with METTL3 deletion whereas AS of EXOC7 correlated with both deletion and gain of METTL3 in invasive breast carcinoma." (PMID 36725888, 2023).
cardiomyopathy (4 papers, 2022 to 2025). A disease of the heart muscle or myocardium proper. "METTL3 increases miR-143-3p expression to inhibit protein kinase C ε (PRKCE) transcription to exacerbate cardiomyopathy (CM) firing in MI/reperfusion (MI/R) injury." (PMID 41194259, 2025). "Downregulating METTL3 and upregulating FTO in obese cardiomyopathy mitigates lipid accumulation and cardiomyocyte death brought on by high-fat diets." (PMID 40001550, 2025).
diabetic foot ulcer (4 papers, 2021 to 2024). "In this paper, our findings demonstrated that ADSCs enhance VEGFR3-mediated lymphangiogenesis via METTL3-mediated VEGF-C m6A modification to improve wound healing of diabetic foot ulcers, indicating that ADSCs can be applied for the clinical treatment of DFU." (PMID 34773968, 2021).
gallbladder cancer (4 papers, 2023 to 2025). "Mechanistically, DCA in gallbladder cancer promotes the dissociation of METTL3 from the MTC (METTL3-METTL14-WTAP) complex, which inhibits the miR-92b-3p expression in an m6A-dependent manner." (PMID 38365891, 2024). "This is highly consistent with our conclusion that when gallbladder cancer cells consume excessive exogenous lipids, the RNA methylation level and METTL3 continue to upregulate." (PMID 38519939, 2024). "In gallbladder cancer, DAC exhibited a possible therapeutic value for those with METTL3 high expression through disturbing METTL3/miR‐92b‐3p related cancer progression." (PMID 36162823, 2023). "We proceeded to investigate whether METTL3 and METTL14 regulate the processing of pri‐miR‐146a in gallbladder cancer cells." (PMID 40785027, 2025). "In gallbladder cancer, it is elucidated that reduced‐deoxycholic acid (DAC) failed to disrupt METTL3 assemble with methyltransferase complex, assisting METTL3‐m6A‐dependent pri‐miR‐92b processing." (PMID 36162823, 2023).
Hypertension (4 papers, 2021 to 2025). The presence of chronic increased pressure in the systemic arterial system. "Taken together, these results highlight the critical role of the YY1/Mettl3 axis in mitigating hypertension and regulating blood pressure under both normal and hypertensive conditions." (PMID 40795179, 2025). "More recently, METTL3, one of the m6A writers, has been shown to promote hypoxia-induced hypertension in pulmonary arteries." (PMID 34200988, 2021). "Additionally, our results demonstrate a clinically relevant role for the YY1/Mettl3 axis in mitigating hypertension and regulating blood pressure under both normal and hypertensive conditions." (PMID 40795179, 2025). "Moreover, our results highlight the clinically relevant role of the YY1/Mettl3 axis in mitigating hypertension and regulating blood pressure under both normal and hypertensive conditions." (PMID 40795179, 2025). "For instance, in hypertension, METTL3 might regulate the signaling pathways that control vascular tone and resistance, whereas in diabetic vasculopathy, it might influence the pathways involved in glucose metabolism and oxidative stress." (PMID 39834386, 2024). "This should not benefit from the improvement of blood pressure, because a previous report has shown that caudal vein administration of AAV9-shMETTL3 inhibiting METTL3 expression in the artery did not influence hypertension induced by Ang-II." (PMID 35836108, 2022).
inflammatory bowel disease (4 papers, 2023 to 2026). A spectrum of small and large bowel inflammatory diseases of unknown etiology. "Bacteroides fragilis toxin inhibits METTL3 expression and its associated m6A activity, enhancing pro-inflammatory responses and exacerbating inflammatory bowel disease progression." (PMID 41376856, 2026). "Previous research has shown that Bacteroides fragilis toxin suppresses METTL3-mediated m6A methylation in macrophages, thereby promoting intestinal inflammation and exacerbating inflammatory bowel disease." (PMID 41376856, 2026). "In inflammatory bowel disease, aberrant expression of METTL3, YTHDC1, and other modifiers in macrophages affects their polarization states, barrier-repair capacity, and inflammatory responses, positioning them as critical regulators of immune homeostasis." (PMID 41376856, 2026). "Inflammatory bowel disease (IBD) exhibits paradoxical m6A regulatory dynamics: METTL3 and FTO demonstrate elevated expression concomitant with METTL14 and HuR downregulation." (PMID 40963968, 2025).
ischemia (4 papers, 2024 to 2025). A hypoperfusion of the BLOOD through an organ or tissue caused by a PATHOLOGIC CONSTRICTION or obstruction of its BLOOD VESSELS, or an absence of BLOOD CIRCULATION. "Conversely, another study observed that overexpression of METTL3 reduced cardiomyocyte apoptosis induced by H/R and cardiac injury induced by I/R, suggesting that METTL3 was one of the factors leading to ischemia-reperfusion injury." (PMID 39893158, 2025).
kidney damage (4 papers, 2023 to 2025). "In this study, we provided convincing evidence that upregulated METTL3 and overactivated m6A modifications are closely associated with Pb-induced nephropathy." (PMID 40520008, 2025). "Our study provides the first evidence that METTL3 regulates uric acid excretion by controlling the m6A levels of ABCG2 through the binding of IGF2BP2, and inhibiting METTL3 can effectively alleviate kidney damage caused by hyperuricemia, showing potential as a therapy for HN." (PMID 40100069, 2025). "The protein levels of the renal tubular injury markers (KIM-1 and NGAL) were increased in Pb-induced nephropathy and downregulated in METTL3 cKO mice." (PMID 40520008, 2025). "MeRIP-seq analysis revealed that 915 peaks decreased and 677 peaks increased in Pb-induced nephropathy in METTL3 cKO mice compared with Flox/Flox mice." (PMID 40520008, 2025). "Next, we determined the detailed mechanism by which METTL3 exacerbates Pb-induced nephropathy." (PMID 40520008, 2025). "Compared with Pb-induced nephropathy in METTL3 Flox/Flox mice, correlation analysis of mRNA and m6A modifications showed that 3909 genes were significantly upregulated, whereas 2978 genes were significantly downregulated in cKO METTL3 mice (GSE288167)." (PMID 40520008, 2025). "We then detected the mRNA expression of m6A methyltransferases (METTL3, METTL14, and WTAP) and demethyltransferases (FTO and ALKBH5) and found that METTL3 and FTO mRNA expression was upregulated in Pb-induced nephropathy compared with controls." (PMID 40520008, 2025). "Upregulation of methyltransferase 3 (METTL3) in the kidneys of SLE patients promotes IRF4 - mediated plasma cell infiltration, resulting in kidney damage." (PMID 41181096, 2025). "The protein levels of renal injury markers (KIM-1 and NGAL) were elevated in lead acetate induced nephropathy, while they were downregulated in mice injected with AAV9 packaged METTL3 knockout virus." (PMID 40520008, 2025).
lung squamous cell carcinoma (4 papers, 2021 to 2024). "Our study showed that the molecular phenotype based on the expression of METTL3 may be an independent risk factor affecting the prognosis of lung squamous cell carcinoma." (PMID 34814861, 2021). "In this article, we systematically elaborated that the high expression of METTL3 in patients with lung squamous cell carcinoma can be used as an independent predictor of good prognosis." (PMID 34814861, 2021). "In lung squamous cell carcinoma, reduced KIAA1429, ALKBH5, METTL3, and HNRNPC expressions were predictive of better responses to chemotherapy and immunotherapy." (PMID 36831575, 2023).
medulloblastoma (4 papers, 2022 to 2024). A malignant, invasive embryonal neoplasm arising from the cerebellum. "In paediatric medulloblastoma, high METTL3 expression is associated with increased m6A levels and low survival, and a specific inhibitor of METTL3 slowed tumour progression in a medulloblastoma mouse model." (PMID 36831575, 2023). "The expression levels of METTL3 in lymphoma_Burkitt, meningioma, medulloblastoma, B-cell_lymphoma_other, and T cell_ALL were higher than those in other tumor types." (PMID 36614956, 2022). "Knockdown of key m6A writer genes METTL3 and METTL14 in a group 3 medulloblastoma cell line (D425-Med) decreased cell proliferation and upregulated many M6LSig genes identified in our in silico analysis, suggesting that the signature genes are functional in medulloblastoma." (PMID 39198884, 2024).
metastatic tumors (4 papers, 2021 to 2025). "To further test the hypothesis that METTL3 nuclear localization correlates with metastatic tumors and explore the underlying mechanisms, we characterized three pairs of tumor cell lines with distinct migration/invasion potential." (PMID 36289222, 2022). "Immunohistochemical analysis of subcutaneous tumors and lung metastatic tumors in mice from the sh-METTL3 and sh-NC groups indicated that silencing METTL3 significantly reduced the expression of the M2 macrophage marker CD163 protein." (PMID 38605400, 2024). "Additionally, we found that METTL3 mRNA levels were increased in primary prostate tumor and metastatic tumor tissues in comparison to normal prostate tissues by analyzing several publicly available Genomic Spatial Event (GSE) databases 18-20." (PMID 34335955, 2021).